EGFR (epidermal growth factor receptor)
Diseases named in the same sentence as EGFR in open-access papers (continued):
Sharing a sentence is not in itself a finding about the gene and the disease.
breast carcinoma (continued). "Altogether, the simply prepared AuNPs-TMC can be a promising non-viral carrier for delivery of EGFR-siRNA into breast cancer cells as a therapeutic strategy for tumor growth prevention." (PMID 35517864, 2022). "Among miRNAs modulated by EGFR activation in MSCs, we found miR-23c, whose biological activity in breast cancer cells has not been fully explored." (PMID 35406622, 2022). "Moreover, lapatinib, a dual EGFR/HER2 TKI, showed good efficacy in breast cancer, which made it an independent evolutionary venation in 2017 with continuous attention to date." (PMID 35072634, 2022). "Proteomic profiling in breast cancers has identified PHGDH as one of the proteins expressed specifically in triple-negative breast cancers, which often have a basal-like phenotype defined by positivity for EGFR and CK5." (PMID 35204409, 2022). "The EGFR pathway activated by EREG and the PI3K/Akt/mTOR pathway activated by FGF10 are well known to be part of the mechanisms of resistance to HER2-targeted therapy in HER2-positive breast cancer." (PMID 35954313, 2022). "Through our findings, we demonstrate, for the first time, the role of SCAMP3 in promoting breast cancer proliferation, migration, and invasion, through negative regulation of EGFR degradation, as well as AKT, ERK, and STAT signaling pathways." (PMID 35681787, 2022). "Interestingly, hsa-miR-205 has also been found to target the human epidermal growth factor receptor, HER3, in human ER+ breast cancer cells." (PMID 36096802, 2022). "ANO1 has also been shown to mediate EGFR signalling in HNSCC and breast cancer cells." (PMID 36497413, 2022). "Additionally, EGFR-2-over-expressed SK-BR-3 breast cancer cells, and the growth of estrogen receptor-bearing MCF-7 breast cancer cells was inhibited by the treatment of fisetin." (PMID 36558146, 2022). "YTHDF3 promoted translation of CTNNB1, contributing to proliferation, migration, and maintenance of cancer stem–like properties in ocular melanoma, and mediated breast cancer brain metastasis through increasing m6A-dependent ST6GALNAC5 and epidermal growth factor receptor expressions." (PMID 36183833, 2022). "In addition, GD3 and the EGF receptor have be observed to be colocalized in breast cancer stem cells; in this condition, GD3 participates to EGFR signaling activation." (PMID 35267607, 2022). "It is known that cancer cell-specific molecules known as cancer antigens such as EGFR (colorectal cancer), GD2 (neuroblastoma), HER2 (breast cancer), VEGFR2 (gastric cancer), Nectin-4 (bladder cancer), or TROP2 (triple-negative breast cancer) are expressed on the surface of cancer cells." (PMID 36546903, 2022). "Currently, CAR-NK has been vigorously tested in breast cancer treatment targeting different breast cancer antigens including HER2 and EGFR, and EGFR-CAR-NK cells could be potentially used to treat patients with TNBC exhibiting enhanced EGFR expression." (PMID 35795050, 2022). "Furthermore, in a proof-of-concept study, eight surface proteins (EpCAM, CD44, HER2, EGFR, IGFR, CD81, CD63, CD9) on model exosomes derived from breast cancer cells were analyzed." (PMID 35198078, 2022). "EGFR, one of the important members of the EGFR tyrosine kinases family, is found to be overexpressed in approximately half of TNBC and has a significant regulatory ability in breast cancer progression and malignant transformation." (PMID 35935930, 2022). "The breast cancer cell lines further split into two groups, which corresponded to their HER2 status—an important prognostic marker based on the assessment of the expression level of the epidermal growth factor receptor 2 (HER2/EGFR)." (PMID 35994503, 2022). "Using breast cancer human cell lines MDA-MB-468 and SKBR3 as in vitro models, the authors have shown that the EGFR-imprinted fluorescein-labelled nanoMIPs with size 150–200 nm specifically recognized MDA-MB-468 EGFR-positive cells, but not SKBR3 EGFR-negative cells." (PMID 35425427, 2022).
breast carcinoma (continued). "In vitro characterization of the imaging and therapeutic agent showed low nanomolar binding to EGFR-positive colorectal cancer and breast cancer cells with (DLD-1, SNU-C2B, SW620) or without (HT-29 and MDA-MB-231) mutations in KRAS." (PMID 36145664, 2022). "In the breast cancer xenograft model, reduction of MMP-1 expression significantly inhibited breast cancer growth, brain metastasis, and lung metastasis through reducing TGFa release and phosphor-EGFR expression." (PMID 35037689, 2022). "Among the detected catalytic receptors, the most relevant to cancer growth, proliferation and differentiation, and breast cancer specifically, were the Tyr protein kinases of the EGFR/ERBB, FGFR and IGFR families of growth factor and hormone binding receptors (Ca)." (PMID 35760832, 2022). "Together with the previously established role of TRAF4 in binding to the C terminal juxtamembrane region of HER1(EGFR) and participating in EGFR signaling activation, our findings further support the oncogenic roles of TRAF4 in breast cancer through increasing the HER2 signaling pathways." (PMID 35864174, 2022). "Importantly, the inhibited EGFR/AKT signaling pathway is responsible for the anti-proliferative and anti-migration activities of actein on breast cancer cells." (PMID 34294040, 2021). "It was also demonstrated that induction of ACTA2 by EGFR and HER2 dimerization is regulated through a JAK2/STAT1 signaling pathway and that abnormal ACTA2 expression accelerates the invasiveness and metastasis of breast cancer cells." (PMID 34211976, 2021). "In contrast, genes often associated with the basal-like subtype and a poor prognosis such as MCL1, CTNNB1, EGFR, or SOX4 were found in the basal-like patient GSM519217 suggesting that the generated networks are capable of extracting breast cancer subtype-specific features." (PMID 33706810, 2021). "In addition, CAR-T cells-derived exosomes that express antibodies that can recognize EGFR (epidermal growth factor receptor) and HER2/CD340 showed promising anti-tumor activity in breast cancer." (PMID 33808645, 2021). "Prolactin receptor (PRLR) and epidermal growth factor receptor (EGFR/ERBB) signaling pathways activated by prolactin (PRL) and epidermal growth factor (EGF), have a major role in the mammary gland development and in the etiology of breast cancer, respectively." (PMID 34572912, 2021). "The biomarkers with the most evidence as highlighted in this paper which may have prognostic implications on breast cancer in older women include and are under reported in the current literature include: BCL2, cyclin E, EGFR, LKB1, MUC1 and CKs." (PMID 34165702, 2021). "Whether ESB attenuates cell growth and triggers apoptosis in other cancer cell types with EGFR TKI resistance, such as pancreatic and breast cancer cells, is also an important issue in predicting the possibility of applying ESB to various cancer types." (PMID 34068421, 2021). "Multiple pre-clinical investigations showed efficacy of NK-CAR cells targeting HER2 in HER2+ breast cancer, tissue-factor in TNBC, epithelial cell adhesion molecule (EpCAM) in both HER2+ and TNBC and epidermal growth factor (EGFR) in all breast cancer subtypes." (PMID 34135901, 2021). "The oncogenic role of long intergenic non-protein coding RNA 885 (LINC00885) is correlated with early breast cancer progression; which may promote cell proliferation and survival through EREG/EGFR and FOXM1 pathways." (PMID 34884633, 2021). "These interconnected downstream signaling pathways activated by EGFR/HER2 and PRLR cooperation may enhance proliferation, survival, migration, and invasiveness of breast cancer cells." (PMID 34572912, 2021). "The irreversible pan-HER inhibitor neratinib (N), which covalently binds to the kinase domain of HER1/EGFR, HER2, and HER4, has shown clinical promise leading to its FDA approval for extended treatment of early-stage HER2+ breast cancer in the adjuvant setting following T-based therapy." (PMID 34045483, 2021).
breast carcinoma (continued). "Therefore, miR-7 has been found to affect the resistance of breast cancer cells to ADR, and its upregulation can enhance the effects of ADR through the suppression of EGFR/PI3K signaling." (PMID 34804971, 2021). "Clinically, the interaction between BRK and EGFR has wide implications, as BRK may potentially be a factor for the low efficacy of anti-EGFR drugs in breast cancer treatment." (PMID 33391524, 2021). "The choice of treatment therapies depends on the types of breast cancer, including triple-negative breast cancer, HER2 (human epidermal growth factor receptor 2)-negative cancer, and hormone receptor (HR)-positive breast cancer, and HER1-positive diseases." (PMID 34959830, 2021). "Therefore, diminishing the expression of ER, PR, EGFR, HER2, Pgp, and NF-κB should be an important strategy to inhibit the growth and drug resistance of breast cancer cells." (PMID 34135981, 2021). "Moreover, in breast cancer cells, estrogens upregulate the S1P-SK1 pathway, and the produced S1P trans-activates EGFR via S1P3." (PMID 34201962, 2021). "However, p68 knockdown did not alter the phosphorylation and expression of other growth factor receptors, including EGFR and FGFR, in the breast cancer cells." (PMID 34659545, 2021). "In addition, a recent large-scale pharmacogenomics study reported co-occurring resistance between EGFR-RTK inhibitors and chemotherapy in breast cancer." (PMID 34404439, 2021). "The findings collected from this study supported that miR-182-5p delivered by breast cancer cell-derived EVs aggravated the development of breast cancer, which was related to its inhibition on the CMTM7 expression and activation on the EGFR/AKT signaling pathway." (PMID 34294040, 2021). "In gastric cancer, EGFR overexpression correlated significantly with AR overexpression, and a negative correlation was observed in breast cancer." (PMID 34681618, 2021). "Prolactin through PRLR can activate both EGFR and HER2 downstream signaling pathways which in turn leads to activation of other oncogenic growth factors that promote growth, survival, and proliferation of breast cancer cells." (PMID 34572912, 2021). "Taken altogether, our findings demonstrates that EVs secreted by breast cancer cells could carry miR-182-5p to aggravate breast cancer through downregulating CMTM7 expression and activating the EGFR/AKT signaling pathway." (PMID 34294040, 2021). "In addition, a phase I study of neratinib, an EGFR, HER2, and HER4 inhibitor, has shown clinical activity in breast cancer." (PMID 34591414, 2021). "MiR-133b played tumor suppressing roles in several malignancies through regulating in gastric cancer, targeting Sox9 in breast cancer, negatively regulating EMP2 in glioma, targeting methyltransferase DOT1L in colorectal cancer, and targeting EGFR in esophageal squamous cell carcinoma." (PMID 33816233, 2021). "B6H12 treatment also acutely inhibited EGF-induced EGFR tyrosine phosphorylation in breast cancer stem cells but not in differentiated breast cancer cells." (PMID 33925464, 2021). "Besides the classic breast cancer targets, such as ER, PR, HER2, EGFR, and recently, GRPR, other targets such as FA and nucleolin have also shown some promise for theranostics of breast cancer." (PMID 33986665, 2021). "Upon intravenous injections, the construct, equipped with the anti-epidermal growth factor receptor (EGFR) CL4 aptamer as a specific ligand for tumor-targeting, resulted able to drastically inhibit breast cancer growth, with nearly undetectable toxicity and immune responses in mice." (PMID 36046085, 2021).
breast carcinoma (continued). "This notion is also supported by our observation that all types of chimeric GE11-MrNV VLPs showed little binding to EGFR-negative MCF7 breast cancer cell line and no significant increase in the binding was observed when compared to the N-MrNV." (PMID 34400669, 2021). "This dual-receptor-targeted agent was specifically bound and internalized by breast cancer cells that expressed HER2, or EGFR, or both, and showed high absorbed radiation doses with 36–119 Gy in the cell nucleus treated with 177Lu-AuNPs-trastuzumab-panitumumab." (PMID 33986665, 2021). "Our correlation analysis revealed that EGFR expression was strongly correlated with expressions of mTOR (r= 0.262–0.496) and FGFR1 (r= 0.203–0.348) in liver, lung, kidney, glioblastoma, colon, head and neck, and breast cancers." (PMID 33842373, 2021). "Also, elevated levels of phosphorylated EGFR and ERK were observed in leptin treated breast cancer cells compared to untreated cells." (PMID 34389732, 2021). "The breast cancer subnetwork is found to contain (i) valid biomarkers including PIK3CA, PTEN, BRCA1, AR and EGFR; (ii) validated drug targets TOP2A, CDK4, HDAC1, IL6, BRCA1, HSP90AA1 and AR; (iii) synergistic drug targets EGFR and BIRC5." (PMID 35053185, 2021). "6-Gingerol has been determined to bind to the EGF receptor in breast cancer cells and blocked phosphorylation without affecting the amount of total EGFR protein." (PMID 33925065, 2021). "In breast cancer cells, HER4 expression is low compared to EGFR and HER2 expression." (PMID 34885957, 2021). "In the case of EGFR regulation in lung and breast cancers, DHHC20 is likely to be the physiologically relevant DHHC enzyme, given that DHHC20 is expressed in multiple lung and breast cancer cell lines." (PMID 34610265, 2021). "In addition to activation by homodimerization, enhanced by overexpression of the receptor in breast cancer, HER2 can dimerize with other ErbB family members such as the epidermal growth factor receptor (EGFR)." (PMID 34441794, 2021). "Using a subset of 747 breast cancer tissues from the previously published TCGA dataset, which included 3467 tumors profiled for 181 functional oncoproteins each, we examined EGFR/pEGFR expression levels in TNBC and non-TNBC tumors." (PMID 34638492, 2021). "As a m6A reader, YTHDF3 was overexpressed and clinically correlated with breast cancer brain metastases (BCBM), suggesting that YTHDF3 overexpression was indispensable for multiple steps of BCBM through facilitating ST6GALNAC5, GJA1, EGFR, and VEGFA expressions." (PMID 34952600, 2021). "Unlike HER2, monotherapies directed toward EGFR or in conjunction with other adjuvant therapies do not provide clinical benefit to breast cancer patients, suggesting a more active mode of resistance." (PMID 33128042, 2021). "We agree with the authors, however, we also believe that the expression of EGFR in breast cancer is still not deliberated in its entirety." (PMID 34754042, 2021). "Further, mRNA expression databases for breast cancer patients available online, also did not indicate correlation between mRNA levels of EGFR and CSMD1." (PMID 34404439, 2021). "It was shown to be of no significant importance in breast cancer and does not play any role in its malignant phenotype through the EGFR wild type is positive." (PMID 34582442, 2021). "Moreover, the incubation of the MDA-MB-231 cells with curcumin led to the reorganization of the fatty acid profile of the breast cancer cell membrane, accompanied by the modulation of p-P44/42 MAPK, ERK1/2, and EGFR expression." (PMID 34298639, 2021).
breast carcinoma (continued). "On the basis of above literature and findings, we proposed the hypothesis that breast cancer cell derived-encapsulated miR-182-5p regulates the CMTM7/EGFR/AKT signaling pathway, thus contributing to the development and progression of breast cancer." (PMID 34294040, 2021). "The EGFR and Src-mediated STAT3 signalling pathway is activated in TamR cells, and inhibition of STAT3 may be a potential target in tamoxifen-resistant breast cancer." (PMID 34407787, 2021). "As a dual kinase inhibitor of human epidermal growth receptors EGFR and HER2 for breast cancer treatment, lapatinib is a substrate for ABCG2 and P-glycoprotein (P-gp), another ATP-binding cassette family protein commonly involved in multidrug resistance to cancer chemotherapy." (PMID 34545713, 2021). "For breast cancer, EGFR inhibitors have not yet been successful in universally producing good response rates." (PMID 34165702, 2021). "EGFR antibody or specific kinase inhibitors can block the TGF-α/EGFR signaling pathway and prevent breast cancer growth induced by TGFA overexpression, suggesting that this pathway may play an important role in cancer treatment." (PMID 32020849, 2021). "HER2 is a member of the epidermal growth factor receptor (EGFR) family of homologous transmembrane receptor tyrosine kinases (RTK) present in 20–30% of breast cancers, having an important role in the progression of the disease, associated with an aggressive disease course and poor survival." (PMID 34503260, 2021). "For instance, EGFR is known to form complexes with PGRMC1, in a PGRMC1 dimer-dependent manner and both experimental strategies (siRNA and AG-205) led to reduced EGFR levels in breast cancer cells." (PMID 34680104, 2021). "Moreover, EGFR and HER2 amplification after breast cancer surgery favor metastasis and it has a considerable prognostic value as biomarker for invasive breast carcinoma." (PMID 34572912, 2021). "Gene amplification is the most frequent genetic alteration in breast cancer with MYC, CCND1, epidermal growth factor receptor (EGFR), fibroblast growth factor receptor (FGFR), CDK4, and MDM2 being the genes most frequently amplified in primary and recurrent breast tumors." (PMID 33996588, 2021). "Moreover, up-regulation of IGF1R is used by breast cancer cells as a mechanism of resistance to HER2, EGFR and anti-estrogen inhibitors." (PMID 34441794, 2021). "Using an anti-EGFR antibody, we confirmed the expression of EGFR on MDA-MB-231 breast cancer cells." (PMID 35052426, 2021). "In this regard, agents targeting EGFR have also been extensively investigated in canine and feline cell lines of OSCC, OSA, TCC and mammary carcinoma, but only the use of EGF‐anthrax toxin has been reported in the clinical setting, for the treatment of canine invasive TCC." (PMID 33664868, 2021). "EGFR and HER2 dimerization modulated ACTA2 through the JAK2/STAT1 signaling pathway and ACTA2 gene abnormalities accelerated the invasion and metastasis of breast cancer cells." (PMID 34179721, 2021). "EGFR is overexpressed in IBC and other types of breast cancer." (PMID 32883032, 2020). "In addition, many prognostic markers of BRCA have been reported: CD24, EGFR, CXCR 4 genes can predict the metastasis and prognosis of breast cancer." (PMID 33365308, 2020). "We determined whether impairing actin polymerization could disrupt ligand-induced dimerization of receptor tyrosine kinases in two human breast cancer cell lines, low EGFR-expressing MCF-7 and high EGFR-expressing MDA-MB-231." (PMID 33050232, 2020). "Clinical studies of EGFR-targeted therapies within the context of breast cancer have been discouraging; however, these trials were largely designed without selection for and treatment of EGFR-expressing triple-negative patient tumors." (PMID 33256808, 2020).